INS (insulin)
Diseases named in the same sentence as INS in open-access papers (continued):
Sharing a sentence is not in itself a finding about the gene and the disease.
Hypoglycemia (continued). "Due to the large amount of insulin administration in our patients, oral antidiabetic drugs had little effect on hypoglycemia, so they did not enter the model." (PMID 33015194, 2020). "Children with PPHH after Nissen fundoplication have an abnormally exaggerated secretion of the insulin secretagogue glucagon-like peptide 1 (GLP-1) which may contribute to the exaggerated insulin surge and resultant hypoglycemia." (PMID 32185602, 2020). "An 86- year- old male was admitted to the emergency department with hypoglycemia diagnosed with non-pancreatic neuroendocrine tumour (NET) on lung secreting insulin." (PMID 34394252, 2020). "As negative-control group, insulin-treated diabetics with neither hypoglycemia nor hypertensive crisis at admission were included." (PMID 33292431, 2020). "KP-exposed mice receiving enteral saline developed hypoglycemia between 24 and 72 hpi, with no increase in circulating insulin." (PMID 32977395, 2020). "The criteria for CHI diagnosis was a non-suppressed insulin and/or C-peptide level at the time of hypoglycaemia." (PMID 32027664, 2020). "This study carefully controlled for the administration effect of IV insulin, which alters blood glucose levels and contributes to negative metabolic states and hypoglycemia in certain patient populations." (PMID 33100956, 2020). "Similar anti-IDs were revealed in patients in many cases of “cryptogenic” hypoglycemia; they are common for the insulin resistance of B-type and were registered both in patients who received insulin injections and in those who had never used exogenous insulin." (PMID 32481667, 2020). "The addition of DPP-4 inhibitors to insulin therapy for adult patients with type 2 DM can significantly reduce HbA1c levels without increasing the occurrence of hypoglycemia." (PMID 33224988, 2020). "Compared with placebo, addition of lixisenatide to basal insulin improved HbA1c and reduced PPG, without increasing hypoglycemia risk." (PMID 31956422, 2020). "In humans, increased GH occurred in a small proportion of patients with spontaneous hypoglycemia (<2.2 mmol/L or 40 mg/dL) independent of insulin levels." (PMID 33148883, 2020). "Carbohydrate intake and/or insulin reduction is typically required for activities lasting >30 min in a non-fasting state, to prevent hypoglycaemia." (PMID 32533229, 2020). "Because BRIGHT was undertaken in insulin-naive individuals without a history of severe hypoglycaemia or hypoglycaemia unawareness, there were not enough severe hypoglycaemic events to evaluate this outcome." (PMID 31984443, 2020). "After 6 h of fasting, apparent hypoglycemia did not occur in healthy rats implanted with the device containing recombinant human insulin (GTT-1 and GTT-2)." (PMID 32555343, 2020). "It is, however, unclear how an individual would not develop hypoglycaemia as a consequence of this higher insulin secretory response." (PMID 32385603, 2020). "Those on insulin were more likely to develop hypoglycemia but no case with true gestational diabetes developed hypoglycemia." (PMID 33519707, 2020). "It is not clear how insulin effects, hypoglycemia, and thrombin would, together, act on CRRs regulating astrocytes in the hindbrain." (PMID 32320636, 2020). "The patient subsequently required 7 days of high-dose dextrose infusion in order to avoid hypoglycemia, with no further insulin needed during this period." (PMID 32342025, 2020). "Two subjects (subject 1 and 6) received a second dose of insulin because the first injection did not achieve clinically-relevant hypoglycemia." (PMID 33277531, 2020). "Unexplained hypoglycemia mimicking that of hyperinsulinism with no detectable insulin should alert the physician to a possible insulin transducing defect." (PMID 32157856, 2020). "They required temporary discontinuation of insulin and/or metformin, and none of them had hypoglycemia or ketoacidosis." (PMID 32699704, 2020).
Hypoglycemia (continued). "We present a rare case of a 43-year-old male patient admitted with recurrent episodes of severe non-ketotic and non-insulin-mediated hypoglycemia due to IGF-II mediated disease and ACTH-dependent Cushing's syndrome." (PMID 32231811, 2020). "The optimization coefficient (γ) was used to calculate the optimized insulin dosage in ITT, which resulted in a significantly higher rate of successful induction of adequate hypoglycemia with a single insulin dose compared to the conventional coefficient (92.9 vs. 60.6%, P < 0.001)." (PMID 32328036, 2020). "In the Empagliflozin as Adjunctive to Insulin Therapy-2 and−3 studies, empagliflozin add-on to insulin improved glycemic control and weight change without increasing hypoglycemia in patients with T1D." (PMID 32973680, 2020). "Cutting-edge machine learning algorithms, such as deep-learning algorithms, have been used in glucose forecasting but have not yet been applied to estimations of insulin dosage adjustments or hypoglycemia prevention." (PMID 32517068, 2020). "(1987) at Yale University unprecedently demonstrated that phlorizin completely normalized insulin sensitivity in diabetic rats without hypoglycemia—was a connection made between SGLT2 inhibitors and the treatment of diabetes." (PMID 33041801, 2020). "Many anti-infectious agents were one-time doses, to minimize resistance, and insulin, an easy source for accidental hypoglycemia, was not prescribed by visiting mission physicians." (PMID 33094073, 2020). "However, prior work has shown that the timing of insulin delivery both before and following a meal (for CSII users) can help reduce postprandial hyper- and hypoglycemia." (PMID 32517068, 2020). "The first generation sulfonylureas continually induce the secretion of insulin regardless of the blood glucose levels, which consequently results in hypoglycemia." (PMID 32847055, 2020). "No severe hypoglycemia requiring assistance from other individuals occurred; all patients rapidly recovered following calorie intake and insulin dose titration." (PMID 32149152, 2020). "Since these hormones stimulate insulin release glucose-dependently, DPP4 inhibitors lower blood glucose levels with no significant risk of hypoglycemia." (PMID 33195481, 2020). "Eleven episodes of defined hypoglycemia occurred in six women, all receiving insulin therapy, but none after a corrective dose of insulin." (PMID 33519707, 2020). "In patients with T1D, insulin+sotagliflozin decreased the HbA1c level, daily insulin dose, and body weight without hypoglycemia compared with insulin monotherapy." (PMID 32973680, 2020). "Fear of hypoglycemia and lack of social support and interference with social life were the next most common reasons for insulin discontinuation." (PMID 32569176, 2020). "Treatment of hypoglycemia in NkHH can be very difficult, because there is no beneficial medical therapy to counteract insulin synthesis or secretion." (PMID 32157856, 2020). "Of those who achieved adequate hypoglycemia with single dose of insulin, the two groups did not significantly differ with regard to their blood glucose nadirs (P = 0.828)." (PMID 32328036, 2020). "Administration of BPF99 reversed the early impairment of insulin-mediated hypoglycemia and returned the curve to the pattern seen in negative controls fed a chow diet only." (PMID 32054943, 2020). "In summary, changes in cerebral blood flow index was measured with diffuse correlation spectroscopy (DCS) during insulin-induced acute hypoglycemia in nondiabetic subjects with normal awareness of hypoglycemia." (PMID 33277531, 2020). "These individuals had higher insulin concentrations at the start of exercise when compared to their counterparts that did not display hypoglycemia." (PMID 32982972, 2020). "Second interesting pattern disclosed in our study is that treatment with insulin secretagogues did not influence the occurrence of hypoglycemia." (PMID 32151247, 2020).
Hypoglycemia (continued). "All events occurred under treatment with intravenous insulin; hence, no patient suffered from spontaneous hypoglycemia." (PMID 32448392, 2020). "If adequate biochemical hypoglycemia (plasma glucose, ≤ 2.2 mmol/l) is not achieved, it would be necessary to give a second injection of insulin." (PMID 32187262, 2020). "This was suggested to likely be due to insulin-induced hypoglycemia rather than to the hyperinsulinemia per se." (PMID 32150819, 2020). "After cessation of insulin secretion in nondiabetics, glucagon is the first line of defense against hypoglycemia prior to activation of sympathetic responses." (PMID 32382023, 2020). "Patients suffering from HI/HA syndrome display protein-induced insulin secretion, fasting hypoglycemia and increased ammonia levels independent of protein consumption." (PMID 32143698, 2020). "We recruited eight non-diabetic subjects (6 females) undergoing an insulin-induced hypoglycemia test for the assessment of pituitary function." (PMID 33277531, 2020). "Reasons for suboptimal management include inadequate titration of insulin, fear of hypoglycaemia, inadequate insulin regimens, lack of a structured education programs, and costs." (PMID 32569176, 2020). "Among the 15 participants in group with a cut-off value for hypoglycemia of < 3.0 mmol/L, 7 participants were not receiving insulin secretagogue therapy." (PMID 32151247, 2020). "Second, many factors (e.g., insulin dose and carbohydrate consumption), which are largely involved in glycemic control and in preventing exercise-induced hypoglycemia, have not been addressed in the current work." (PMID 33192548, 2020). "Evidence of CNS involvement in glucose homeostasis also comes from a study in which mice that moved from a warm to a cold environment had a coordinated reduction in both insulin secretion and insulin sensitivity, despite the absence of hypoglycemia." (PMID 31133864, 2019). "This study also identified that being older, married, prescribed insulin and not being admitted to hospital for hypoglycaemia during the past six months were predictors of a higher problem-solving ability score (p < 0.05)." (PMID 31647820, 2019). "The presently available data suggest that hypoglycemia, rather than hyperinsulinemia, is responsible for insulin-induced hypoglycemic peripheral neuropathy." (PMID 31356602, 2019). "Because DPP-4 inhibitors effectively lower postprandial glucose levels and decrease the probability of hypoglycemia, DPP4-inhibitors could harmonize the safety and action of insulin treatment." (PMID 30611254, 2019). "In a parallel‐design RCT, 72‐hour infusion of GLP‐1 did not reduce intravenous insulin requirement nor the rate of hypoglycaemia compared with saline control, although there was less plasma glucose variability with GLP‐1." (PMID 31141838, 2019). "Observational studies of insulin degludec (degludec) with hypoglycemia events prospectively recorded are lacking." (PMID 31397845, 2019). "Two recent randomized clinical trials showed that the addition of the insulin-dosing component allowed the system to increase time in target and reduce mean morning glycemia, without deteriorating the performance in hypoglycemia mitigation." (PMID 30922295, 2019). "Incidence of hypoglycemia per dialysis session (3.3% vs. 0.7%, P = 0.02) and symptoms related to hypoglycemia (6.9% vs. 0.7%, P < 0.001) were more frequent in the nonadjusted-insulin group than in the adjusted-insulin group." (PMID 31828166, 2019). "For Hypo1day the fully adjusted odds of hypoglycemia were greater for basal insulin non-users but not for basal insulin users." (PMID 31775749, 2019). "Paul, MN, appears to be an effective and practical method for delivering insulin directly into the brain without significant hypoglycemia." (PMID 31354415, 2019). "IN glucagon (3 mg) has been shown to be noninferior to IM glucagon (1 mg) in treating insulin-induced hypoglycemia in adults with T1D." (PMID 31349701, 2019).
Hypoglycemia (continued). "Hypoglycemia influences treatment compliance, which can result in an increase in complications due to lack of disease control as a result of modifying the insulin dose in response to hypoglycemia." (PMID 31584770, 2019). "In 10 of the 12 patients congenital hyperinsulinism was confirmed, whilst in two patients insulin was either not measured at the time of hypoglycaemia or was shown to be appropriately suppressed." (PMID 32832699, 2019). "However, there were key differences between the trials, such as the starting dose of insulin, titration algorithms, targets for self‐monitored blood glucose (SMBG) and hypoglycaemia definitions." (PMID 30924567, 2019). "The incidence of confirmed (≤3.9 mmol/L and <3.0 mmol/L) and/or severe hypoglycaemia was similar between self‐ and physician‐managed titration, regardless of prior insulin use." (PMID 30851006, 2019). "For instance, the response to hypoglycemia seems to be fast, occurring within 60 min in one study, whereas the CNS-mediated insulin effects are not evident until after 180 min according to some studies." (PMID 31133864, 2019). "Incidence of hypoglycemia per dialysis session (3.3% vs. 0.7%, P = 0.02) and symptoms related to hypoglycemia (6.9% vs. 0.7%, P = 0.001) were more frequent in the nonadjusted-insulin group." (PMID 31828166, 2019). "Aspart is as safe and effective as human insulin when in base therapy with NPH insulin and may offer some benefits for postprandial glycemic control and for the prevention of severe hypoglycemia." (PMID 30786308, 2019). "In individuals without T1D, insulin levels decrease at the onset of moderate-intensity PA to counter the enhanced glucose uptake and protect individuals from hypoglycemia." (PMID 30787908, 2019). "Additionally, using closed-loop insulin delivery may be insufficient to prevent hypoglycemia during exercise, whereas combining closed-loop insulin with additional snacking of 15–30 g of carbohydrate before exercise prevented all cases of hypoglycemia in a recent study." (PMID 31835538, 2019). "None of the babies were on insulin at the time, and there were no clinical concerns about hypoglycaemia." (PMID 30232094, 2019). "They stimulate insulin secretion and inhibit glucagon secretion by elevating endogenous GLP-1 concentrations without an intrinsic hypoglycaemia risk." (PMID 31275246, 2019). "It is known that the physiological glucagon response to insulin-induced hypoglycemia is impaired in T1DM, but not in T2DM." (PMID 31620088, 2019). "That means the mechanism of OOPs hypoglycemia was not through promoting insulin secretion, but rather by changing the insulin resistance level thus leading to increased uptake and utilization of glucose." (PMID 30717466, 2019). "Patients’ educational level, marital status, not being admitted to hospital for hypoglycaemia during the past six months, and being prescribed insulin were significant predictors of high problem-solving ability." (PMID 31647820, 2019). "Skipping meal, doing physical exercise without taking food, and inappropriate dose of insulin were found to be the most common reasons for the recurrent episodes of hypoglycemia." (PMID 31093506, 2019). "The urine ketone bodies and circulating insulin autoantibodies were negative during hypoglycemia episodes." (PMID 31094068, 2019). "The personalised insulin calculator demonstrated a marked reduction in hypoglycaemia, with no episodes occurring in patients administered insulin according to the calculator’s recommendations (ITT group)." (PMID 30737563, 2019). "Insulin levels are unlikely to be helpful in the setting of a child with poor intake presenting at 6 months to 6 years of age with non-recurrent hypoglycemia and ketonuria, and not surprisingly, most children had insulin levels below the assay lower range." (PMID 31700521, 2019).
Hypoglycemia (continued). "Here, we report the first case of intractable hypoglycemia due to co-secretion of insulin from gastric cardia adenocarcinoma (GCA) and lung adenocarcinoma (LA), as confirmed by immunohistochemical staining for insulin." (PMID 29166433, 2019). "Type 1 diabetics with a normal response to glucagon however are able to recover from hypoglycemia without insulin infusion." (PMID 31829209, 2019). "In this study, the insulin level was not affected by canagliflozin therapy and no patient experienced hypoglycemia." (PMID 31167663, 2019). "To support the involvement of IL-1 in modulation of hypoglycemia-induced counterregulatory responses, we showed that mice lacking both IL-1a and b (IL-1a/b KO) displayed less severe insulin-induced hypoglycemia than wild type controls." (PMID 30996341, 2019). "Older age, being educated, being married, having T2DM, prescribed insulin therapy, and not having been admitted to hospital for hypoglycaemia were important predictors of patients’ problem-solving ability (p < 0.05)." (PMID 31647820, 2019). "In hospitalized patients who were treated with insulin, inpatient mortality occurred in 7.6% of hospitalizations with severe hypoglycemia and 3.8% in those without." (PMID 31393971, 2019). "In addition to CGM, advanced insulin pumps include low-glucose suspension and predictive low-glucose suspension (PLGS), which can prevent episodes of hypoglycemia." (PMID 31623111, 2019). "GLP-1 stimulates glucose-dependant insulin secretion and inhibits glucagon release, lowering blood glucose only in the presence of insulin and not resulting in hypoglycaemia." (PMID 30865008, 2019). "In addition the odds of hypoglycemia were increased with SBB compared to carvedilol, again only in basal insulin users." (PMID 31775749, 2019). "A missed meal, too much exercise, alcohol, or not enough food for the amount of insulin administered can lead to hypoglycemia." (PMID 31138204, 2019). "Interestingly, insulin tolerance test (ITT) showed that recovery after hypoglycemia was delayed in KDM5B-KO mice (p < 0.05), supporting that KDM5B-KO mice maintain normoglycemia through improved insulin sensitivity." (PMID 31467927, 2019). "Diverse drugs were being used by patients of the hypoglycemia subgroup (DPP-4 inhibitor by 1 patient, biguanide alone by 1, multiple oral glucose-lowering drugs by 1, and insulin mixture by 1 patient), but none developed severe hypoglycemia." (PMID 30815039, 2019). "In both cases, the hypoglycemia is nonketotic or hypoketotic due to the effect of insulin in suppressing fat breakdown and ketone formation." (PMID 31700521, 2019). "The STZ-induced diabetic mice were injected with insulin (10 U/kg, ip) to match their basal glycemia with that of non-diabetic control 1-h prior to being evaluated for their hypoglycemia counterregulatory response." (PMID 30503832, 2019). "Participants in this study were not particularly concerned regarding risks of hypoglycemia and weight gain after insulin injection." (PMID 30807441, 2019). "This therapy must be used with caution as the amount of insulin injected can lead to hypoglycemia if the shot of glucagon is not administered as well." (PMID 30893335, 2019). "Nevertheless, SLGT2 inhibitors have shown significant decreases in blood glucose and HbA1c levels regardless of insulin amount or sensitivity with no weight gain or hypoglycemia, which are common side effects in conventional antidiabetic drugs." (PMID 30901912, 2019). "Furthermore, insulin Glargine U-100 (Sanofi, FRA) and insulin Detemir (Novo Nordisk A/S, DEN) basal dose reductions were also found to prevent hypoglycemia over 24 h after performing an acute bout of physical exercise." (PMID 31174360, 2019). "On postoperative day (POD) five, the patient's insulin infusion was held due to non-symptomatic hypoglycemia." (PMID 31523559, 2019).